CASP1 (caspase 1)
Diseases named in the same sentence as CASP1 in open-access papers (continued):
Sharing a sentence is not in itself a finding about the gene and the disease.
Hyperglycemia (continued). "Studies have indicated that hyperglycaemia increased the production of ROS to activate caspase-1 and trigger the caspase-1-dependent pyroptotic cell death, suggesting that pyroptosis mediates important pathological changes in diabetic cardiomyopathy." (PMID 29062465, 2017). "Recent work demonstrated that TXNIP induced NLRP3 expression, activation of caspase-1, and release of IL-1β in a model of hyperhomocysteinemia or hyperglycemia with podocyte injury." (PMID 27867451, 2016). "Together, these data suggested that the caspase-1-dependent pyroptosis is a contributor to the hyperglycemia-induced cell death in DCM." (PMID 25136835, 2014). "In addition, activation of caspase-1 by both stimuli, hyperglycemia and IL-1β, was mediated by RIP2 as determined by RIP2 knockdown experiments." (PMID 39483336, 2024). "In addition, upstream inhibition of the caspase-1/IL-1β signaling using YVAD-fmk or RIP2 knock down also prevented hyperglycemia mediated cell death of Müller cells." (PMID 39483336, 2024). "Initially, activation of caspase-1 is predominantly driven by hyperglycemia." (PMID 39483336, 2024). "Interestingly, although caspase-1 activation during this feedback signaling is mediated by two distinct stimuli, hyperglycemia and IL-1β, both pathways are controlled by one regulator, RIP2." (PMID 39483336, 2024). "Reports have shown that in “sterile inflammation” RIP2 played a significant role in hyperglycemia-induced caspase-1 activation, thus, we tested whether both stimuli upregulate RIP2." (PMID 39483336, 2024). "Accordingly, we hypothesized that P2X7 receptor expression is strongly activated in H9C2 cells with hyperglycemia injury, causing NLRP3/caspase-1-mediated pyroptosis." (PMID 37685976, 2023). "NF-κB in the renal cortex and NF-κB, IL-18 and Caspase-1 in the renal medulla of the model + LPS group were apparently upregulated, indicating that LPS can promote inflammatory factors by the transcription factor NF-κB in the hyperglycemia model." (PMID 37467292, 2023). "However, NLRP3 and cleaved caspase-1 complex formation increased with hyperglycemia and cytokine challenge but was inhibited by tonabersat treatment." (PMID 33396676, 2020). "Although our study used Müller cells to demonstrate hyperglycemia-induced caspase-1/IL-1β/IL-1R1 feedback signaling, other retinal cells might be capable of producing similar feedback cycles leading to sustained caspase-1 activation and prolonged IL-1β production." (PMID 39483336, 2024). "Hyperglycemia and oxidative stress in the diabetic milieu activate NLRP3, facilitating the cleavage of pro-caspase-1 into active caspase-1, which then promotes the maturation and secretion of key pro-inflammatory cytokines, IL-1β and IL-18." (PMID 40352596, 2025). "Our data also indicate that hyperglycemia induces caspase-1 activation initially but IL-1β sustains caspase-1 activation via caspase-1/IL-1β/IL-1R1 feedback and we identified RIP2 as mediator for both hyperglycemia- and IL-1β-induced caspase-1 activation." (PMID 39483336, 2024). "Studies have shown that in patients with diabetic nephropathy, hyperglycemia can activate NLRP3, which coexists with ASC and pro-caspase-1 to form the NLRP3 inflammasome, and then activates caspase-1." (PMID 36552271, 2022). "It has been reported that hyperglycemia activates NLRP3 inflammasome, thus promoting pro-caspase-1 to caspase-1." (PMID 35034587, 2022). "Previous studies have confirmed that hyperglycemia induced NLRP3 inflammasome activation, while the active caspase-1 induces excessive release of inflammatory cytokines, leading to tight junction disruption and consequent endothelial permeability." (PMID 34631209, 2021). "Hyperglycemia can trigger NLRP3 overactivation and promote the production of cleaved caspase-1, thus accelerating the maturation and release of IL-1β and IL-18, which induce pyroptosis and finally lead to cardiac dysfunction and heart failure." (PMID 35096293, 2021).
Hyperglycemia (continued). "It had been reported that hyperglycemia can activate PYD containing NLRP3 inflammasome, and promote the transformation of pro-caspase-1 to caspase-1, thereby expedite the development of pyroptosis." (PMID 34712670, 2021). "Prolonged hyperglycemia in pancreatic islets induces ROS accumulation, which results in elevation in TXNIP to activate NLRP3 inflammasome activation and to induce caspase-1-dependent IL-1β maturation." (PMID 34631209, 2021). "It has been reported that hyperglycemia activates nucleotide-binding oligomerization domain-like receptor pyrin domain containing (NLRP) 3 inflammasome, thus promoting pro-caspase-1 to caspase-1." (PMID 30250027, 2018). "So, the NLRP3 inflammasome pathway can be synergistically activated by hyperglycemia and AS, with consequently increased mRNA expression of NLRP3, ASC and caspase-1." (PMID 29151018, 2017). "In conclusion, hyperglycemia and hyperlipidemia can lead to the activation of NLRP3 inflammasomes, and their downstream molecules, including caspase-1, IL-1β, and IL-18, in the glomerular mesangium." (PMID 28708885, 2017). "On the other hand, the innate immune response to chronic hyperglycemia by IL-1β, NLRP3 and caspase-1 inflammasome is cyclical." (PMID 22474421, 2012). "In this study we have outlined a mechanism of prolonged caspase-1 activation that contributes to chronic inflammatory events in the diabetic retina and while set in motion by hyperglycemia seemingly becomes independent of its original hyperglycemic insult." (PMID 39483336, 2024). "Although hyperglycemia initially drives caspase-1 activation, over time glucose consumption surprisingly does not seem to serve as mediator of prolonged caspase-1 activity." (PMID 39483336, 2024). "Naringin reduces hyperglycemia, inhibits the proliferation of cells induced by high glucose, and decreases the expression of inflammatory that is mediated by NLRP3 through the NLRP3-caspase-1-IL-1β/IL-18 signaling pathway." (PMID 34371645, 2021). "In conclusion, hyperglycemia activates ALPK1 in renal TECs, leading to phosphorylation of NF-κB, which could contribute to release of the N-terminal domain of GSDMD after cleavage by caspase-1." (PMID 36732854, 2023).
Salmonella Infections (41 papers, 2008 to 2025). Infections with bacteria of the genus SALMONELLA. "By binding to and activating CASP1, invasion protein B (Sip B) causes macrophage apoptosis during Salmonella infection." (PMID 39392284, 2024). "In macrophages, Salmonella infection is associated with pyroptosis, a pro-inflammatory, caspase-1 mediated programmed cell death." (PMID 35711662, 2022). "Casp1−/− and Casp1/11−/− monolayers proved highly susceptible to Salmonella infection and the majority of infected IECs remained intact within the monolayer." (PMID 32282854, 2020). "It has been recently demonstrated that the Casp1−/− mice used in this study are also deficient in Casp11 (also referred to as Casp4), and that Casp11 deficiency in the context of Casp1 deficiency is protective against Salmonella infection." (PMID 23977202, 2013). "Recent studies on Shigella and Salmonella infections implicated caspase 1 activation in programmed cell death that was different from apoptosis induced by the activation of caspase 3; this process was named pyroptosis." (PMID 18447956, 2008). "Within the first 36 h after Salmonella infection the Naip/NLRC4 inflammasome is required for Caspase-1 mediated cell extrusion associated with IL-18 production whereas at a later time point (>72 h post infection) non-canonical inflammasome activation involving Caspase-11 is needed." (PMID 34497340, 2022). "Beyond the intrinsic connection between apoptosis and necroptosis, caspase-1, an essential component of inflammasomes, cleaves apoptosis-associated caspase-7 during Salmonella infection (NLRC4 inflammasome trigger) as well as in response to LPS + ATP stimulation (NLRP3 inflammasome trigger)." (PMID 35563804, 2022). "Since pretreatment with YVAD largely phenocopies ZVAD, these data suggest that caspase-1 is the primary caspase that responds to Salmonella infection in THP-1 cells." (PMID 40162563, 2025). "Caspase-1 level was assessed in RAW264.7 cells after Salmonella infection using Western blot, which reflected Salmonella’s ability to induce macrophage pyroptosis." (PMID 40731965, 2025). "During enteric Salmonella infection, the activation of caspase-1 and the production of IL-1β and IL-18 provide a protective host response." (PMID 38396532, 2024). "Along these lines, a recent report has shown that only combined ablation of all the pathways which drive NLRC4 inflammasome-dependent cell death (deletion of Asc, Caspase 1 and Caspase 11, simultaneously) can protect mice from fatal Salmonella infection." (PMID 38236896, 2024). "While Salmonella infection induced equivalent caspase-1 activation in untreated and muscimol-treated cells, the formation of punctate ninjurin-1 speck-like assemblies was blocked by muscimol." (PMID 37798443, 2023). "Together these results show that PMN Caspase-1 activity and IL-1 signaling are key drivers of protective cell shedding during Salmonella infection of the intestinal epithelium." (PMID 36191054, 2022). "The pyroptotic caspase-1 also cleaves apoptotic PARP1 in response to inflammasome-activating triggers, and loss of caspase-1 during Salmonella infection leads to activation of apoptotic proteins instead." (PMID 35563804, 2022). "It is suggested that the Salmonella strain with the ability to enhance caspase-1 activation can strengthen the cell’s defense against Salmonella infection." (PMID 29523140, 2018). "In this study, intravenous infection pathway was used to analyze the function of caspase-1 activation enhanced by EscI on the protection of mice against Salmonella infection." (PMID 29523140, 2018). "Caspase-1, a central effector of pyroptosis, is activated in the inflammasome complex during Salmonella infection and has a protective role during Salmonella infection in vivo." (PMID 29628924, 2018).
Salmonella Infections (continued). "It was reported that Salmonella infection stimulated pyroptosis of macrophages, a newly identified program of caspase-1-correlated cellular demise, resulting in cell lysis with release of IL-1β and IL-18." (PMID 26811498, 2016). "Treatment with general DUB inhibitors (such as PR-619 and WP1130) has a negative effect on LPS/ATP-induced deubiquitination of NLRP3 and it also inhibits caspase-1 activation during Salmonella infection, which suggests that DUBs are involved in this process." (PMID 26267804, 2015). "Our studies demonstrate that TLR5 and caspase-1 have modest roles in host defense against wild type Salmonella infection, which is largely due to efficient FlgM-dependent silencing of flagellin expression." (PMID 23977202, 2013). "This analysis reveals that dysregulated flagellin production profoundly attenuates Salmonella infection in all tissues in a caspase-1 dependent manner." (PMID 23977202, 2013). "Caspase-1 has been shown in several publications to provide moderate protection against Salmonella infection." (PMID 24381573, 2013). "Flagellin-deficient Salmonella colonized the cecum, spleen, liver and MLN of Casp1−/− and WT mice equally well, indicating that caspase-1 mediated control of Salmonella infection is dependent on flagellin expression by Salmonella." (PMID 23977202, 2013). "Hence, a relatively prevailing viewpoint has been that caspase-1 activity is necessary for apoptosis to occur in response to Salmonella infection." (PMID 40721578, 2025). "In addition, the Casp1-/—, IL-1β-/—, and IL-18-/—mice also succumbed to Salmonella infection more rapidly than wild-type (WT)-C57BL/6 mice, with markedly higher bacterial burdens in spleens, Peyer’s patches, and mesenteric lymph nodes." (PMID 37155697, 2023). "Studies have shown that Casp1 transcript levels decrease slightly with the progression of Salmonella infection, and the lack of caspase-1 renders the body more susceptible to pathogens." (PMID 34061266, 2021). "Another important function that the ubiquitin modification might have in Salmonella infection of host cells is pro-inflammatory cell death, or pyroptosis, which bypasses macrophage apoptosis during Salmonella infection and is dependent on caspase-1 activity." (PMID 26267804, 2015). "Regardless of the mechanism involved, our results clearly show that caspase-1 activation induced by Shigella or Salmonella infection is not impaired in Pkcδ-deficient macrophages." (PMID 24516390, 2014). "Notably, the Pkcδ kinase was dispensable for caspase-1 activation and secretion of IL-1β induced by Shigella or Salmonella infection." (PMID 24516390, 2014). "Caspase-1 protected mice against WT Salmonella infection, consistent with previous reports." (PMID 23977202, 2013). "The model predicts that Casp11 induced cell death in the absence of Casp1-dependent IL-1B and IL-18 production increases host susceptibility to Salmonella infection." (PMID 23977202, 2013). "Why non-canonical Caspase-11-mediated pyroptosis, like NLRC4-activation accompanied by IL-1β and IL-18 secretion that induces local inflammation and attracts neutrophils, is less potent than Caspase-1-mediated pyroptosis in controlling Salmonella infection remains thus far unclear." (PMID 24381573, 2013). "Interestingly, caspase-2 contains a CARD domain and has been shown to mediate caspase-1 activation during Salmonella infections." (PMID 24350060, 2013). "Interestingly, mice lacking caspase-1 gene expression (Casp1−/−), but not caspase-11 gene expression, are more susceptible to Salmonella infection than mice lacking both caspase-1 and caspase-11." (PMID 31284572, 2019). "Our data indicate that caspase-1 also limits mucosal injury in Salmonella infection, and this may be mediated through caspase-1-dependent control of Salmonella growth, through caspase-1 regulation of mucosal inflammatory responses, or a combination of these factors." (PMID 23977202, 2013).
Salmonella Infections (continued). "However, Salmonella infection of macrophages still activates caspase-1 and induces IL-1β release." (PMID 22563421, 2012). "Beyond these connections, in cells lacking pyroptosis via GSDMD-deficiency, caspase-1 can cleave caspase-3 and Bid to promote apoptotic cell death in response to inflammasome triggers such as LPS priming and poly(dA:dT) transfection, or during Salmonella infection." (PMID 35563804, 2022). "Through the use of in vivo mouse infections as well as enteroid-derived monolayers, we have clarified the contributions of caspase-1 and caspase-11 to the IEC-intrinsic inflammasome and its ability to restrict enteric Salmonella infections." (PMID 32282854, 2020). "Similar to the findings of previous reports, GA treatment inhibited caspase-1 activation, IL-1β maturation and ASC oligomerization triggered by nigericin, cytosolic LPS or Salmonella infection, aside from poly(dA:dT) transfection." (PMID 32312957, 2020). "Previous studies showed that NLRP3 and NLRC4 recruit ASC and caspase-1 in response to bacterial trigger, and both of NLRC4 and NLRP3 are activated during Salmonella infections." (PMID 29594070, 2018). "In that line, Salmonella infection has recently been shown to induce recruitment of both NLRP3 and NLRC4 to the same inflammasome complex along with ASC, caspase-1, and caspase-8." (PMID 28403163, 2017). "Furthermore, we found that inhibition of S1PR3 enhanced dsDNA-induced AIM2 inflammasome and salmonella infection-induced NLRC4 inflammasome activation, as indicated by enhanced caspase-1 cleavage." (PMID 36798132, 2023). "In our study, both CASP1 and IL1β genes were observed upregulated after Salmonella infection, while no significantly dysregulated miRNA were identified to play critical roles in regulation of these genes." (PMID 29391047, 2018). "On the other hand, the NLRC4-dependent caspase-1 activation by Salmonella infection was not considerably affected by the knockdown of Drp1 in macrophages." (PMID 26489382, 2015). "Pyroptosis is an important cell death type that occurs during Salmonella infection, and since DUBs such as UCH-L5 might be relevant in regulation of inflammasomes, we tested caspase-1 activity in cells overexpressing UCH-L5." (PMID 26267804, 2015). "In contrast to the effect seen during Salmonella infection, caspase-1 activation was not inhibited by cytochalasin D during infection of BMMs with the WT V. parahaemolyticus or ΔtdhAS mutant (T3SS1+)." (PMID 23357873, 2013). "However, deletion of both NLRC4 and NLRP3 recapitulates the Caspase-1 phenotype completely, confirming a role for both NLRC4 and NLRP3 during Salmonella infection." (PMID 24381573, 2013). "While the precise nature of this interaction is still a subject of debate, it has been suggested that the NAIP/NLRC4/ASC complex formed after Salmonella infection may recruit NLRP3, potentially amplifying caspase-1 cleavage and subsequent IL-1β cytokine release." (PMID 38124741, 2023). "As caspase-1 KO mice are resistant to Salmonella infection, pyroptosis induced by Salmonella may not be influenced by cIAP-1 in vivo." (PMID 19657383, 2009). "Activation of NLRC4 inflammasome by Salmonella infection and AIM2 inflammasome by exposure to poly(dA:dT) resulted in comparable caspase-1 cleavage between WT and Abcb1b–/– cells (data not shown)." (PMID 36038196, 2022). "A complex containing catalytically active caspase-1, but not ASC triggers cell death but not cytokine secretion, while a distinct ASC-containing focus mediates caspase-1 processing and cytokine secretion, during Salmonella infection." (PMID 23226685, 2012). "Indeed, it was shown that NLRC4 could also activate caspase-1 even in the absence of ASC, to induce pyroptosis, ASC however remains to be crucial for cytokine maturation during Salmonella infection." (PMID 25115174, 2014).